CD4 (CD4 molecule)
Diseases named in the same sentence as CD4 in open-access papers (continued):
Sharing a sentence is not in itself a finding about the gene and the disease.
tumor (continued). "Antigen-specific CD4+ and CD8+ T cells in tumors are functionally exhausted and can be reinvigorated using immune checkpoint inhibitors which result in tumor destruction; however, efficient presentation of tumor antigens appears to be key to ICI efficacy." (PMID 35474500, 2022). "Similarly, adoptively transferred CD4+ T cells specific for an MHC-II-restricted, tumor-specific peptide were found to eliminate MHC-II-negative UV-induced fibrosarcoma 6132A-PRO tumors by an indirect mechanism dependent on IFNγ activation of host cells." (PMID 36159781, 2022). "The increased number of intraepithelial CD8+ T-cells, as opposed to the low stromal CD4+ T-cells, was suggested to represent a link to anti-tumor immunity and has been postulated to inhibit the development of micro-metastasis and further tumor spread." (PMID 36612177, 2022). "Furthermore, we found significantly higher number of CD4+ T cells, but, to our surprise, lower number CD8+ T cells in APR-246-treated tumours." (PMID 36138076, 2022). "CD4+ and TAM depletion on the other hand slightly enhanced the anti-PD-1 efficacy (TGI 81% and 75% respectively), while CD25+ depletion increased tumor efficacy (TGI 92%), suggesting that the Treg and TAM mediated immune suppressive TME countered the anti-PD-1 MOA." (PMID 35228603, 2022). "CTLA-4 is expressed in activated CD4+ and CD8+ T cells, which can prevent activating effector T cells, and its inhibitor can induce T cell activation, promote the activation and proliferation of effector T cells, and enhance the tumor killing ability." (PMID 35321670, 2022). "In addition, CD4 fox p3+ regulatory lymphocytes in liver metastasis contained higher frequencies of PD-L1 and LAG3 than in the primary tumor and peritoneal metastasis." (PMID 36013315, 2022). "If the tumor microenvironment has a large number of CD8 T cells, the lack of tumor-specific CD4 T cells will not be able to mount an immune response and therefore will not destroy the tumor cells." (PMID 36232485, 2022). "Moreover, CD4+ and CD8+ tumor infiltrating lymphocytes (TILs) should be separated prior to TCR sequencing to avoid a bias due to a higher clonality exhibited by CD8+ TILs compared to CD4+, so the clonality in TILs could be due to the high numbers of CD8+ cells." (PMID 35955721, 2022). "However, Ack1 KO mice injected with anti-CD4 and anit-CD8 or both types of depletion antibodies significantly inhibited tumour growth." (PMID 36376335, 2022). "In the CD4+T cell population analyzed, PRI revealed two bin-plot patterns (CD90/CD44/CD86 and CD90/CD44/CD27) and 20 bin plot features for threshold-independent classification of mice concerning ineffective and effective tumor treatment." (PMID 35592315, 2022). "Moreover, we explored the relative contributions of CD4+ and CD8+ T cells to the potency and durability of BsAb-induced cytotoxicity using CD3-engaging BsAb constructs targeting a series of different tumor antigens." (PMID 35990699, 2022). "This has been compounded by a lack of reliable markers that discern tumor-specific Tregs from tumor-specific effector CD4+ T cells and self-reactive Tregs, taking us back to the drawing board due to unpredictable risks of harming peripheral tolerance." (PMID 36248808, 2022). "Blocking PD-1 has been shown to promote T CD4+ cell activity and CD154 expression, cytokine production, dendritic cell maturation, and T CD8 cell proliferation and differentiation, specific to the tumor’s surroundings." (PMID 37305016, 2022). "DCs have been proposed as therapy against cancer because they may induce an effector immune response dependent on CD4+ and CD8+ T lymphocytes to eliminate tumor cells." (PMID 35209237, 2022).
tumor (continued). "Our studies further demonstrated decreased effector CD4+ Th cells, increased Treg and G-type MDSC, as well as upregulation of immune checkpoints on both effector/regulatory cells and patients CD138+ tumor cells in MM, compared to patients with MGUS and SMM or healthy individuals." (PMID 34290359, 2022). "CD4+T cells secrete a variety of cytokines, which directly or indirectly activate other immune cells (such as B cells and CD8 +T cells) and enhance the anti-tumor activity of CTL." (PMID 35126480, 2022). "CD4+ T cell infiltration was present in the interface area around the tumor in the liver surrounding the CCA tumor tissue, while CD8+ T cell infiltration was present inside the tumor." (PMID 36147461, 2022). "Furthermore, during the treatment, the populations of effector Tregs marked by CD4+CD45RA−FoxP3high reduced, and CD8+ T cells in tumor-infiltrating lymphocytes (TILs) augmented (NCT02476123)." (PMID 35585567, 2022). "Meanwhile, we found that the numbers of CD3+ T cells and the CD4+, CD8+ subsets not only in different patients but also in different tumor regions and corresponding normal tissue of the same patient varied greatly in PTC-W and PTC-WO, such as P1 versus P2/P3, and PH1 versus PH2/PH3." (PMID 35720279, 2022). "In vivo studies were carried out to see if the anticancer action could be detected by CD4+ and CD8+ T cell receptors to generate and activate polypeptide-specific tumor-responding T cells in vivo." (PMID 36276155, 2022). "Interaction of the MHC/tumour antigen epitope complex with the T‐cell receptor and costimulatory signals (including CD70/CD27) may lead to the activation of CD4+ and CD8+ T cells." (PMID 36471481, 2022). "Because different subsets of CD4+ T cells and their functions determine the outcomes of mucosal barrier immunity, T-dependent B cell responses, and CD8+ T cell-mediated anti-tumor immunity, alterations in these cells contribute to hampering of anti-cancer responses in the elderly." (PMID 35821823, 2022). "Analysis with the Tumor IMmune Estimation Resource (TIMER) also revealed that FABP6 expression was negatively correlated with the immune infiltration of B cells, CD8+ T cells, CD4+ T cells, macrophages, neutrophils, and DCs." (PMID 36033394, 2022). "Th9 cells are a recently identified subset of CD4+ T cells that produce IL-9 in response to TGF-β and IL-4 in vitro and have been shown to participate in the pathogenesis of allergic inflammation and asthma and play roles in anti-tumor immunity." (PMID 36241625, 2022). "According to the results of the Western blot, CTP significantly increased the levels of CD4, CD8, and IL-2, and reduced the levels of CTLA4 and PD-L1 in the tumor, and CTLA4 and PD-1 in the spleen of ApcMin/+ mice; this underscored the pivotal role of IL-2 in the immune response." (PMID 35662701, 2022). "Altogether, both studies imply that CD4+ and CD8+ T cell responses in tumors are complementary and together might overcome tumor cell heterogeneity and allow for broader tumor cell recognition by T cells." (PMID 35439168, 2022). "Meanwhile, tumor-infiltrating activity might be facilitated in the tumor microenvironment by elevated circulating CD8+ and CD4+ MAIT cells during LC." (PMID 35371315, 2022). "When CD4+ T cells from OTII TCR transgenic mice were activated in vitro and injected intravenously into C57BL/6 mice on day 9 after transplantation of E0771-control-I-Ab/OVA or 3LL-control-I-Ab/OVA, tumor growth was markedly suppressed." (PMID 35094065, 2022). "The increase of tumor infiltrating CD8 + and CD4 + T cells confirmed that the combination of IM@Z + NIR with PD-L1 siRNA could effectively promote the anti-tumor immune response." (PMID 35236356, 2022). "In fact, TIM-3 is widely expressed on T antigenic tumor-specific lymphocytes, in peripheral blood and in tumor-infiltrating lymphocytes (TIL), both CD4+ and CD8+, and overexpressed on so-called exhausted T cells (especially CD8+ and CD4+ Treg Foxp3+) in tumor settings." (PMID 35207500, 2022).
tumor (continued). "As explained in another study, subsets of TILs have an important role on tumor progression and outcomes, as CD8 T cells are key determinants of antitumor immunity, and CD4 T cells can either support this immune response or suppress it, as the case for Treg cells." (PMID 36686160, 2022). "Furthermore, a specialized subset of CD4+ T cells, CD4+CD25+ regulatory T cells (TRegs), effectively hampers anti-tumor immune responses, and this has been proposed as one of the major tumor immune evasion mechanisms." (PMID 35804865, 2022). "Identifying ways to harness the cellular cooperation between these 2 CD4+ and CD8+ TIL subsets could lead to more efficient tumor recognition and control and could potentially aid in tumor destruction." (PMID 35439168, 2022). "Although CD4+ and CD8+ Tcm can inhibit tumor progression, we also found that AQP5 expression might reduce CD4+ Tem in our study." (PMID 35619903, 2022). "The red fluorescence area (CD4+ T and CD8+ T) of the 1MT and GA groups was larger than that in the control group, designating that the single-drug group exhibited increased infiltration of T cells in tumor tissue." (PMID 35875081, 2022). "These immunosuppressive cells include CD4+ T cells, CD8+ T cells, B cells, neutrophils, dendritic cells and macrophages, which can assist immune evasion, thereby promoting the occurrence and development of tumours." (PMID 34953037, 2022). "Increased TIM-3+CD4+ T cells correlated with larger tumors, suggesting more exhausted T cell pool is non-favorable to tumor growth inhibition." (PMID 36419897, 2022). "Furthermore, we found that the levels of CD4+ T cells, CD8+ T cells, and MAIT cells in tumor were significantly decreased in the DM-4T1 group, compared to the 4T1 group." (PMID 35578660, 2022). "Moreover, IRFs were positively correlated with the abundance of tumor infiltrating immune cells in PC, including B cells, CD8+ T cells, CD4+ T cells, macrophages, Neutrophil, and Dendritic cells." (PMID 35012444, 2022). "Analysis of the immune infiltrate of the primary tumours at the time when the tumours started to regress revealed an influx of both CD4+ and CD8+ activated T cells and a reduction in PD-L1+ infiltrating monocytes, providing an explanation for the observed tumour regression." (PMID 35821197, 2022). "Next, we employed lineage-specific markers to annotate clusters into major cell types of the tumor, including T cells (CD3G, CD4, CD8A, CD28, and IL7R), B cells (CD19 and CD20), myeloid cells (HLA-DRA and CD14), fibroblasts (THY1 and ACTA2), and tumor cells (EPCAM and S100A)." (PMID 35634306, 2022). "Results from a combined treatment, comprising Adriamycin, revealed that GLP-Au could reverse the decline in the number of CD4+/CD8+T cells, and generate a strong inhibitory effect on 4T1 tumor growth as well as lung metastasis." (PMID 35664731, 2022). "Tumor-infiltrated immune cells may include cancer-infiltrated cytotoxic T cells (CTLs), memory T cells (CD45RO+), regulatory T cells (CD4+CD25+), tumor-infiltrated macrophages type M1 and/or M2, and dendritic cells." (PMID 35216378, 2022). "It is plausible that the PD-1 blockade induced conversion of CD25+Foxp3+ CD4 Tregs into CD25−Foxp3+ CD4 Tregs38, since we observed the intratumoral transferred CD25+Tregs with PD-1 blockade had decreased tumor egress, along with increased conversion to IFNγ-producing CD25-Tregs." (PMID 35449134, 2022). "The results revealed that the proportion of CD4+CXCR5+CD69+ cells in peripheral blood CD4+ T cells was independent of tumor location in OS patients." (PMID 35081874, 2022). "While, on average, 60% of CD39+ CD4+ Th cells have the DP CD4+ phenotype, our results demonstrated that the remaining cells (DN CD4+ and SP CD4+) were not enriched in tumor-reactive TCRs." (PMID 35439168, 2022).
tumor (continued). "Zhang and co-authors developed gold GLP composite nanoparticles which activated dendritic cells, promoted the proliferation of T killers and Tregs in splenocytes, elevated the percentage of CD4+/CD44+ memory T cells, and reduced tumor weight and metastasis in the 4T1 breast cancer mouse cell model." (PMID 35890166, 2022). "In fact, tumor cells were not able to induce proliferation of CD4+ T-cells even when PD-L1 was blocked, which complicates drawing conclusions about the role of the MHC-II/LAG-3 axis in this important T-cell function." (PMID 35655709, 2022). "By 6 d post-treatment, there was a trend toward increased CD8 T-cell but not CD4 T-cell or natural kill (NK) cell infiltration in tumours." (PMID 35606429, 2022). "Importantly, UCB T cells also mount more effective antitumor responses via faster tumor infiltration with CCR7+ CD8+ T cells and faster induction of cytotoxic CD8+ T cells and CD4+ Th1 cells in the tumor microenvironment." (PMID 35365224, 2022). "In parallel to the changed ratio of CD8+/CD4+ T cells, FVS also revealed an increased number of tumor death in ccRCC-03_PDO and ccRCC-06_PDO after toripalimab treatment, exhibiting anti PD-1 dependent tumor killing." (PMID 36544542, 2022). "In line with published data, cytotoxicity against the tumor cells was independent of the CD4/CD8 ratio of the CAR-T cells, confirming the equal cytolytic activity of CD4+ and CD8+ T cells." (PMID 36298713, 2022). "While studying the tumor microenvironment of this patient population, we found that in RDEB patients affected by cSCC, the expression of CD4 lymphocytes is lower than in the peritumoral infiltrate found in primary cSCC and in RDEB patients with pseudoepitheliomatous hyperplasia." (PMID 35207500, 2022). "Based on limited overlap between the TCR repertoires of tumor infiltrating effector CD4+ T cells and Tregs, some have argued that pTregs do not play a prominent role in the TME." (PMID 36248808, 2022). "Although baseline LAG-3 and PD-1 levels in tumour samples did not correlate with response, we observed increased frequencies of memory CD4+ and effector CD8+ T cells in the posttreatment tumour specimens of patients with favourable treatment response." (PMID 36289334, 2022). "Immune-infiltrating CD4 + T cells are involved in anti-tumor function, which not only contributes to the activation of CD8 + T cells but also helps in the generation and preservation of memory cytotoxic T lymphocyte responses." (PMID 35596183, 2022). "The median CD20/(CD4+ CD8) and CD8/(CD4+ CD8) ratios in IP3 IMs were between those of IP1/2 IMs and IP1/4 Paras, which might indicate a compromised status between the host and tumor." (PMID 35228530, 2022). "Overall, ISV with FOLactis could induce tumor regression mainly dependent on CD8+ T and NK cells, with other immune cell subsets, such as macrophages and CD4+ T cells, playing lesser roles in tumor rejection." (PMID 36463242, 2022). "We indeed found a strong association in multiple malignancies using the infiltration scores of six immune cell types (B cell, CD4+ T cell, CD8+ T cell, neutrophil, macrophage, and dendritic cell) accessible in the Tumor Immune Estimation Resource (TIMER) database and obtained from TCGA." (PMID 35251007, 2022). "Differences between subsets of CD4+ and CD8+ T cells may also depend on their spatial localization and their interaction with LLT1-expressing tumor and/or immune cells." (PMID 35185935, 2022). "Furthermore, activated CD4+ helper and CD8+ cytotoxic lymphocytes (CTLs) stimulate type 1 immunity, which leads to anti-tumour activity by secreting tumour necrosis factor (TNF)- α, interferon (IFN)- γ, and other cytotoxins." (PMID 35804943, 2022). "FAST-FNA analysis on TNIKi-treated tumors surprisingly revealed that the administration of NCB or MBZ substantially increased the number of tumor-infiltrating CD8+ T cells at day 9 of treatment and, to a lesser extent, CD4+ T cells at earlier time point of TNIKi treatment." (PMID 35675910, 2022).
tumor (continued). "The effect was more pronounced on CD4+ rather than CD8+ T cells considered to be the major anti-tumor T cells." (PMID 36876140, 2022). "Furthermore, we found that the numbers of CD3+ T cells and their CD4+, CD8+ subtypes in tumor samples were generally higher than those in normal tissue in PTC-WO and moreover, the number of CD3+ T cells was negatively associated with TCR clonality in PTC-WO." (PMID 35720279, 2022). "Immune phenotypic analysis of tumor-infiltrating T cells revealed that co-administration of CXB to the combination of CTX and ICB boosted the activation of CD8+ and CD4+ T cells, which displayed significantly higher production of IFNγ and surface expression of the activation marker CD44." (PMID 35440553, 2022). "Notably, CD4+ and CD8+ T cells were found to be crucial for the anti-metastatic response, and cured mice were able to resist tumor rechallenge, suggesting production of immune memory." (PMID 35955613, 2022). "While cognate CD4+ Th cells are responsible for mediating protective effects, bystander CD4+ T cells ultimately exit the tumor without providing a tangible antitumor benefit." (PMID 35703176, 2022). "Both CD8+ and CD4+ Tcells also showed increased expression of the immune checkpoint molecules PD-1,LAG-3 and TIM-3 in KPAR tumours.Furthermore, KPAR tumours also contained a significant proportion of PD-1/LAG-3double-positive CD8+ T cells which were completely absent in KPB6tumours." (PMID 35930804, 2022). "T-follicular helper cells are significantly correlated with high expression of PD-L1, which promotes tumor immune response, and CD4 T cells play a negative role in tumor immunity." (PMID 36307842, 2022). "It has become increasingly apparent that CD4+ T cells possess an extraordinary capacity to induce tumor rejection as principal effectors rather than as subsidiary helpers to cytolytic T cells." (PMID 35874660, 2022). "Similar to Tc1 cells, CD4+ T helper 1 (Th1) cells that are essential for generating cellular immunity do not directly kill tumor cells." (PMID 35053375, 2022). "In this study, the Univariate analysis showed that age, ATB administration, CD4+, CD8+ and CD16 + 56+ T cell levels, but not sex, smoking status, tumor pathological type, or D-Dimer, are associated with MFS in patients with stage III NSCLC." (PMID 36384523, 2022). "CD4+ T cells contain two diverse subsets of helper T cells, namely, Th1 cells, which produce TNF-α, IFN-γ, IL-2, and IL-12 to mediate antitumor effects, and Th2 cells, which generate IL-4 and IL-10 and foster tumor growth by suppressing the host immune system." (PMID 36212483, 2022). "We further examined whether other immune cells were affected by SENP3 deficiency in macrophages, including myeloid‐derived suppressor cells (MDSCs), CD4+ and CD8+ T cells isolated from tumor tissues, spleen, and tumor‐draining lymph nodes." (PMID 33932085, 2022). "Furthermore, the deduction of MDSCs by the combination therapy increased CD3+, CD4+, and CD8+ T cell infiltration to tumor tissues more than anti-PD-L1 single therapy." (PMID 35785030, 2022). "As for tumor microenvironment, RES subtype exhibited increased recruiting activity of CD8 + T, T helper 1, and natural killer cells, and RET subtype with increased recruiting activity of CD4 + T and regulatory T cells in silico." (PMID 35879731, 2022). "The knockout of these genes or the inhibition of mTOR signaling activity were sufficient to enhance memory-like CD4+ T cell responses and to provide prolonged help to CD8+ T cells to achieve target tumor cell killing, underscoring a central role for mTOR signaling in this context." (PMID 35990699, 2022). "Pretreatment ALC did not correlate with the number of tumor-infiltrating CD4-, CD8-, or CD68-positive cells." (PMID 35385334, 2022). "Antibody depletion of CD4+ T cells did not decrease the efficacy of MSC-CD3-CD40L therapy, whereas depletion of CD8+ T cells led to a complete loss of tumor control in both MC38 and CT26." (PMID 36073543, 2022).